PPIAL4C (peptidylprolyl isomerase A like 4C)
Description:
PPIases accelerate the folding of proteins. It catalyzes the cis-trans isomerization of proline imidic peptide bonds in oligopeptides (By similarity).
Synonyms: COAS-2
Gene: Protein-coding gene on chromosome 1 (149,583,848 to 149,584,607, forward strand). Ensembl gene ENSG00000288867.
Subcellular location: Cytoplasm
Gene Ontology:
Molecular function: cyclosporin A binding; peptidyl-prolyl cis-trans isomerase activity
Biological process: protein folding
Cellular component: cytoplasm
Genetic constraint (gnomAD): Loss-of-function variants: 0 observed, 0.5 expected, observed/expected ratio (o/e) 0, 90% interval 0 to 1.84. That is too few expected variants to judge how well the gene tolerates losing a copy. Missense variants: 0 observed, 11.11 expected, observed/expected ratio (o/e) 0, 90% interval 0 to 0.27. Synonymous variants: 0 observed, 4.85 expected, observed/expected ratio (o/e) 0, 90% interval 0 to 0.62.
Homologues: Orthologues: zebrafish ppifa (70% identical), zebrafish ppiab (69% identical), Caenorhabditis elegans cyn-3 (66% identical), Caenorhabditis elegans cyn-7 (66% identical), zebrafish ppiaa (65% identical), Caenorhabditis elegans cyn-2 (64% identical), Caenorhabditis elegans cyn-1 (62% identical), Caenorhabditis elegans cyn-9 (51% identical), Drosophila melanogaster Cyp40 (49% identical), Drosophila melanogaster Moca-cyp (47% identical). Paralogues in human: PPIAL4A (98% identical), PPIAL4E (98% identical), PPIAL4F (98% identical), PPIAL4G (98% identical), PPIAL4H (98% identical), PPIAL4D (98% identical), PPIA (87% identical), PPIF (67% identical), PPIE (62% identical), PPID (61% identical), PPIB (57% identical), PPIC (54% identical), and 10 more.
Diseases named in the same sentence as PPIAL4C in open-access papers:
PPIAL4C is named in the same sentence as 1 disease in open-access papers, as found by Europe PMC text mining. Sharing a sentence is not in itself a finding about the gene and the disease. The quoted sentences say what the papers report.
cancer (1 paper, 2022). A tumor composed of atypical neoplastic, often pleomorphic cells that invade other tissues. "Interestingly, six genes, including ALS2, DAPL1, HS6ST1, IGFBP2, MGC12982, PPIAL4C, are selected in all predictions, i.e., when no samples is removed, or one cancer type data is removed." (PMID 35349572, 2022).